IL1B (interleukin 1 beta)
Diseases named in the same sentence as IL1B in open-access papers (continued):
Sharing a sentence is not in itself a finding about the gene and the disease.
infection (continued). "The concentration of IL-6 was significantly increased by 12 dpi, peaked at 20 dpi and decreased afterwards whereas the concentrations of IL-1β and IL-2 remained unchanged along the infection." (PMID 30455700, 2018). "Infection with the hlyU mutant also resulted in decreased secretion of IL-1β and IL-6, the two Th17-polarizing cytokines, although the decreases in the expression of DC surface markers and cytokine mRNAs were not significant." (PMID 30283443, 2018). "Third, there was greater activation of inflammasomes during AF2122 infection than G18 infection, resulting in the production and release of a greater amount of mature, active IL-1β protein." (PMID 29263113, 2018). "The caspase-4-dependent response to F. novicida LPS is a physiological response as it fully controls IL-1β release and cell death upon infection of hMDMs." (PMID 29339744, 2018). "Combined treatment with YVAD-CHO caspase-1 inhibitor and PGE2 before infection with Y. enterocolitica led to a decreased IL-1β secretion as expected." (PMID 30429830, 2018). "Locally, IL-1β can induce cytokine production, enhance T cell activation and antigen recognition, and direct neutrophils to the site of injury or infection." (PMID 30583612, 2018). "Similar to vancomycin, both MP1102 and NZ2114 significantly suppressed the production of IL-1β at 24 h (18.7–49.5 pg/ml) after infection." (PMID 29523806, 2018). "The production of IL-1β during cell injury, infection, or inflammation occurs primarily in monocytes and macrophages, in addition to nonimmune cells, such as fibroblasts and endothelial cells." (PMID 30116155, 2018). "In this study, we used live S. aureus to cause an acute infection, and the RAW264.7 cells secreted up to 250 pg/ml of IL-1β at 4 h." (PMID 29667111, 2018). "Pro-IL-1β is presumably released by cells dying in response to AF2122 infection and accounts for the greater proportion of IL-1β present in the supernatants." (PMID 29263113, 2018). "During in vitro infections, IL-1β secretion was lower in alveolar macrophages from caspase-1/11, NLRP3 or AIM2 KO mice than in WT controls." (PMID 30456207, 2018). "IL-1β is responsible of the promotion of phagocyte activity favoring the host immune response against infection." (PMID 29970179, 2018). "We found that free ISG15 enhances the production of IFN-γ and IL-1β during murine infection with Toxoplasma gondii." (PMID 29891555, 2018). "Neutrophils also produce IL-1β in infection and inflammatory diseases (32, –, 34) and use this two-signal model for inflammasome activation." (PMID 29440572, 2018). "Release of mature IL-1β into the extracellular environment is essential for IL-1β to exert its host defense function in response to infections and injuries." (PMID 30515160, 2018). "In contrast, the average fold change in IL-1β mRNA level in response to AF2122 infection was 2.1-fold higher than that induced by G18 infection at 24 hpi, which was not a significant difference." (PMID 29263113, 2018). "In this regard, we show that the production of mature IL-1β is significantly increased upon infection with an HCMV mutant that is unable to express pp65." (PMID 30332797, 2018). "We verified that IL-10 was able to inhibit inflammasome activation by A28006 infection, resulting in low levels of IL-1β as well as LDH production." (PMID 30518854, 2018). "ATP-induced IL-1β release only plays a subordinate role in during infection, where other inflammasomes and other mechanisms of caspase activation dominate." (PMID 29922281, 2018). "Cytokines, such as TNF-α and IL-1β, regulate the inflammatory responses by playing important roles in host defence, infection, and pathogenesis of the disease." (PMID 30127737, 2018). "IL-1β protein produced by human MDM in response to M. tuberculosis infection has been shown to be proportional to the infection dose." (PMID 29263113, 2018).
infection (continued). "WT mice also showed increased levels of TNF-α and IL-1β after infection (respectively), inflammatory cell recruitment to the knee joint, and tissue inflammatory cell infiltration demonstrated histologically when compared with ST2−/− mice." (PMID 29867945, 2018). "Overall, our data demonstrate that lack of CgYapsins augments the inflammatory response of macrophages during infection in an IL-1β–dependent manner, thereby underscoring the regulatory role of CgYapsins in the host innate immune response." (PMID 29491142, 2018). "While we anticipate that caspase-1 mediated activation of pro-IL-1β will contribute to activated IL-1β levels in infection scenarios, we expect that a portion of the IL-1β produced will be the result of increased gene expression." (PMID 30101649, 2018). "Neutrophils control infectious pathogens by a variety of mechanisms, including the release of the cytokine IL-1β, a major driver of inflammation during infection." (PMID 29440572, 2018). "We also observed a temperature effect on the gene expression of IL-1β in Atlantic cod; both alone and in combination with infection, with the most pronounced effect between weeks 2-5 pi." (PMID 30564213, 2018). "4(b)) and 2(h) post infection displayed significantly increased levels of IL-1α, IL-1β, IL-6, and IL-8 when compared with the uninfected, time-matched control." (PMID 30101649, 2018). "The presence of free ISG15 enhances the production of IL-1β by CD8α+ DCs present at the site of infection." (PMID 29891555, 2018). "Both P. aeruginosa wild-type strains induced ~30 pg/mL of IL-1β secretion in hCFs after 6 h of infection." (PMID 28469996, 2017). "The liver showed slightly elevated TNFα as well, but we found decreased IL-1β and KC level after the cell wall mutant infection." (PMID 28713338, 2017). "Upon pathogen recognition, macrophage-derived cytokines such as TNF-α, IL-1α and IL-1β trigger the response to local infection by activating lung epithelial cells." (PMID 28931863, 2017). "Mtb is endowed with the unique ability to regulate fundamental inflammatory processes, such as recruiting immune cells to the focus of infection to produce proinflammatory cytokines (IL-1β, TNF-α, etc.)." (PMID 28642632, 2017). "We also evaluated for cellular cytokine transcripts, such as IFN-α, IFN-β, and interleukin-1β (IL-1β), which are normally induced upon infection." (PMID 29246315, 2017). "We measured significant levels (2 to 3-fold) of IL-1β, at 8 days up to 6 weeks post-infection, and increased IL-6 levels (ca. 5-fold) at day 5 post-infection." (PMID 29085807, 2017). "IL-1β production at 18 hr post-infection with all three bacteria was markedly reduced in cells overexpressing UBE2L3 and significantly increased in cells in which UBE2L3 expression was silenced." (PMID 28147281, 2017). "The double-stranded DNA sensor AIM2 is known to recruit ASC to trigger puncta formation in response to infection, leading to caspase-1 activation and IL-1β and IL-18 release." (PMID 28771586, 2017). "For example, GBS hemolysin and inflammasome components can trigger pro-IL-1β processing and IL-1β release by neonatal neutrophils, amplifying their recruitment to sites of infection." (PMID 28293548, 2017). "We then used ELISA to measure IL-1β, IL-18 and IL-17 levels in serum and/or tissue homogenates of mice 3 days after infection with 109 STm." (PMID 29253868, 2017). "At 96 h after infection, the mRNA expression of IL-1β was downregulated in all the organs (liver, kidney, and lung), while TNF-α was downregulated only in the kidney." (PMID 28791016, 2017). "In contrast, most (6/8) male mice treated with the combination of anti-IL-1α plus anti-IL-1β antibodies (anti-IL-1α/β) developed orofacial abscesses beginning 5–7 days after infection, pathognomonic for disseminating dentoalveolar infections." (PMID 28358036, 2017).
infection (continued). "Subsequent cleavage of pro-IL-1β and pro-IL-18 into their mature forms is critical for the host response to infection and is accompanied by caspase-1-dependent inflammatory cell death—pyroptosis." (PMID 29085810, 2017). "Loss of both ATM and DNA-PKcs (Scid:AtmC/C:Lyz2Cre/+) leads to a significant reduction in IL-1β production in response to infection of BMDMs with L. monocytogenes." (PMID 28362262, 2017). "Infection of the BAL cells with different M. tuberculosis strains resulted in a clear induction of mainly macrophage associated cytokines such as MIP-1α and IL-1β." (PMID 29125874, 2017). "On the other hand, lack of TLR9 signaling significantly attenuated the secretion of IL-1β following IOE infection in TLR9-/- BMM, and abrogated S6 phosphorylation." (PMID 29049365, 2017). "The proinflammatory cytokines IL-1β and TNF-α are considered primary mediators of septic shock and are also associated with infection-induced preterm delivery." (PMID 28957335, 2017). "In liver tissues, higher levels of IL-1β, IL-6, and IL-8 were induced by treatment with V. vulnificus alone after 3, 6, 12, 24, and 48 hours, but infection in fish treated with TP4 or co-injected with TP4+V." (PMID 28085905, 2017). "To analyse the mechanism of hypo-responsiveness in more detail, we constructed a kinetic model accounting for the activation of the NF-κB signalling pathway in lung epithelial cells by infection with L. pneumophila, direct stimulation with flagellin or IL-1β." (PMID 28931863, 2017). "Interleukin 1 beta (IL-1β) is the most potent pro-inflammatory cytokine that is crucial in host-defense responses to infection and injury." (PMID 28914761, 2017). "The activation of IL-1β is regulated by two pathways in response to pathogen infection: transcription of pre-IL-1β mRNA and proteolytical processing of pre-IL-1β protein by caspase-1." (PMID 28060938, 2017). "Taken together, PMN recruitment to the site of infection is largely dependent on IL-17, but only in synergy with innate inflammatory cytokines such as IL-1β." (PMID 28424682, 2017). "IL-1β serves as a potent stimulator of heterophil recruitment and is essential for pathogen infection; IL-8 is a chemoattractant for heterophils and monocytes produced following acute infection." (PMID 28086922, 2017). "In patients and mice, EV-A71 infection enhances the expression of IL-1β, IFN-γ, and TNF-α, which can induce IL-6 expression." (PMID 29233145, 2017). "IL-6 is a pleiotropic cytokine secreted by a variety of cells in response to various stimuli, such as infections and other cytokines, including IL-1β, interferon gamma (IFN-γ), and TNF-α." (PMID 29233145, 2017). "The pro-inflammatory cytokines (such as Il1b) produced by myeloid cells, including macrophages, induce early responses against infection or injury." (PMID 28229859, 2017). "Our result suggested that Th1 cytokines, TNF-α and IL-1β expression increased in cag+ infection compared to cag− infection." (PMID 28286572, 2017). "ATG7 silencing did not affect priming, as shown by the lack of effect in either WT or pearl DCs on TNFα secretion after STm infection or on pro-IL-1β production after stimulation with LPS-beads." (PMID 29253868, 2017). "It is well known that macrophages secrete several inflammatory mediators in response to Mtb-infection, including IL1β and IFNβ." (PMID 28863187, 2017). "IL-1β is one of 11 members of the IL-1 family and acts as a crucial regulator of sterile inflammation in addition to host responses to infection." (PMID 28067797, 2017). "A higher level of IL-1β was detected on day 13 pi, although an early peak of this cytokine was also detected at 12 hr after infection." (PMID 28895840, 2017). "We cannot deny the possibility that upregulation of IL-1β and other pro-inflammatory cytokines by infection also induces these processing proteases." (PMID 27714503, 2017).
infection (continued). "This is because the expression of IL-1β mRNA in MG-63 cells, by each tested bacterium, was initiated at adhesion time period (3 h) and continued to increase until 12 h post infection." (PMID 28800779, 2017). "As compared to control THP1 cells expressing YFP (THP1Ctrl#1), THP1YFP-UBE2L3 cells showed diminished LPS-induced pro-IL-1β and therefore released ∼2- to 6-fold less IL-1β after nigericin treatment or STm infection." (PMID 28147281, 2017). "Myd88-/- mice demonstrate a 60% reduction in IL-1β at 8 hours post-infection in comparison to WT mice, confirming the essential role of MyD88 for IL-1β induction." (PMID 28704551, 2017). "The model also shows almost 2-fold increase in the production of NF-κB after infection which then leads to the activation of IL1β and IL8." (PMID 28932213, 2017). "The BAL IL-1β levels in control (145.6 pg/mL) and asthmatic mice (100.7 pg/mL) after seasonal infection were significantly higher than the A(H1N1)pdm09-infected groups (control/A(H1N1)pdm09: 16.5 pg/mL, asthmatic/A(H1N1)pdm09: 45.0 pg/mL), respectively." (PMID 28831046, 2017). "Among those tested the pro-inflammatory mediators IL1α, IL1β, IFNγ and IL-6 and numerous chemokines were substantially elevated in male lungs as early as 21 days post infection." (PMID 28887521, 2017). "Large molecular complexes known as inflammasomes regulate the release of IL-1β from immune cells in response to infection and injury." (PMID 28761045, 2017). "Absence of caspase-6 was associated with significantly increased mRNA expression levels of two cytokines in a very early stage after infection, the anti-inflammatory IL-10 and the pro-inflammatory IL-1β, that are marker of poor disease outcome." (PMID 28686630, 2017). "Taken together, our results corroborated that the IL-1β-induced degradation of IRAK-1 in lung epithelial cells can negatively impact IL-8 expression upon infection by L. pneumophila, suggesting its crucial role in regulating hypo-responsiveness." (PMID 28931863, 2017). "It has been demonstrated that infection of monocytes and macrophages by some strains of Chlamydia, including Chlamydia trachomatis, Chlamydia muridarum, and Chlamydia psittaci, leads to IL-1β secretion consequent to the activation of Caspase-1." (PMID 28660207, 2017). "Skin explants infected with aprV2 and aprB2 D. nodosus released IL1β in the culture media, which accumulated between 4–16 h and 16–28 h post infection." (PMID 28959685, 2017). "During infection, the activated astrocytes generate IL-1β and IL-6 through the p38/IκB- or TNFα/NF-κB-mediated pathway and delay neuronal death in pathological situations with H2O2 generation." (PMID 28950910, 2017). "IL-1β and IL-18 content in the supernatant of peritoneal macrophages following 4 h of infection (MOI = 50 or 100) was significantly higher than those in the unfected control (P < 0.05)." (PMID 28468643, 2017). "With the exception of dendritic cells, all populations of myeloid cells analyzed, including macrophages, monocytes and neutrophils expressed more pro-IL-1β after infection in RAG+CD8 mice compared with RAG mice." (PMID 28192528, 2017). "Twenty-four hours post-infection, the mRNA levels of IL-6, IL1B, and IL-8 were lower in the testosterone-pretreated cells in a dose-dependent manner (p < 0.05) compared to those of the positive control." (PMID 28665978, 2017). "When the inflammasome is assembled in cells of the innate immune system, it induces caspase-1 activation, followed by production of IL-1β or IL-18; IL-1β and IL-18 contribute to host defense during infection." (PMID 28369146, 2017). "The early and sustained activation of NLRP3 and IL-1β production contributes to the infiltration of neutrophils and monocytes to sites of infection where these cells continue to secrete cytokines resulting in a “cytokine storm”." (PMID 28418930, 2017).
infection (continued). "This is a highly inflammatory form of programmed cell death, which has been proposed to mediate IL-1β secretion under condition of strong stimulation such as infection with intracellular pathogens." (PMID 28421072, 2017). "In particular, α-hemolysin destabilizes the dermis by inducing tissue barrier disruption and host cell cytolysis, and increasing the level of the pro-inflammatory cytokine IL-1β in infected tissue, which induces a neutrophil influx to the site of infection." (PMID 28536677, 2017). "In human monocytes, particularly the secreted GRA15 protein of T. gondii is responsible for IL-1β induction and the release of IL-1β is a direct consequence of inflammasome activation after infection." (PMID 28604600, 2017). "IL-1β production by PBMCs in relation to fatigue has also been studied during the acute phase of an infection and in the phase of persisting symptoms." (PMID 28109186, 2017). "Secretion of the pro-inflammatory cytokine IL1β has been shown to be strongly induced upon infection of macrophages and epithelial cells with B. cenocepacia." (PMID 28651010, 2017). "On the other hand, there were 2.04-, 2.38- and 2.84-fold changes in IL-1β precursor protein expressions in mice with low-, medium- and high-dose infections at 20 wpi, respectively." (PMID 29273062, 2017). "In contrast, S. aureus 6850 infection alone resulted in a marginal induction of these cytokines and chemokines, while IL-1β and CXCL8 mRNA levels were elevated after bacterial infection." (PMID 28195157, 2017). "TNF-α and IL-1β, in particular, are key mediators of the signal transduction initiating immediate immune cell activity upon release from the site of infection." (PMID 28572772, 2017). "Early after infection, TNFα, IL-1β, IL-6, IL12p70 and IFN-β levels were lower in supernatants from Hdac6-/- cells than in those from Hdac6+/+ cells, and this difference held at 12 and 24 hpi." (PMID 29281743, 2017). "The pro-inflammatory cytokines, tumor necrosis factor-α (TNF-α), interleukin-1β (IL-1β) and IL-6, are the first secreted cytokines in a local infection, such as IE." (PMID 29078765, 2017). "In the current study, our findings show how P. aeruginosa stimulates IL-18 and IL-1β expression in hCFs during the early stages of infection and they describe an important role for bacterial flagellin." (PMID 28469996, 2017). "Infection in pregnancy elevated the serum inflammatory cytokines IL-1β, IL-12p40, GM-CSF and eotaxin from 2 to 10 times whereas it significantly reduced RANTES." (PMID 29176767, 2017). "Male and female innate immunity and acquired immunity are quite different: the male body contains more IL-1β and TNF-α than the female body, but for these cytokines, infection and damage are closely linked." (PMID 28915872, 2017). "IL-1β exerts its protective action against infections by rapidly recruiting neutrophils to inflammatory sites." (PMID 28345644, 2017). "The activation of caspase-1 and IL-1β production induced by SEA in infected HSCs was measured at various time points after the start infection." (PMID 28808303, 2017). "Cytokines such as TNF-α, IL-1β, and IL-6 play key roles in various inflammatory processes, such as the acute-phase reaction, tissue damage, and infection." (PMID 28524081, 2017). "As IL-1β is a cytokine with a major role to initiate the inflammatory process after an infection, this was also showed during the HSV-1 infection." (PMID 28222752, 2017). "When THP-1 cells were infected with Ms_PE_PGRS41 combined with a stimulatory dose of LPS, TNF-α, IL-6 and IL-1β expression were significantly increased compared to the response to LPS or Ms_PE_PGRS41 infection alone." (PMID 28440335, 2017). "IL-1β and IL-6 both stimulate the proinflammatory response during infection, resulting in severe inflammation, and are known to be upregulated following inoculation with bacteria." (PMID 28970274, 2017).